ABO (ABO, alpha 1-3-N-acetylgalactosaminyltransferase and alpha 1-3-galactosyltransferase)
Diseases named in the same sentence as ABO in open-access papers (continued):
Sharing a sentence is not in itself a finding about the gene and the disease.
Crohn disease (3 papers, 2017 to 2024). A gastrointestinal disorder characterized by chronic inflammation involving all layers of the intestinal wall, noncaseating granulomas affecting the intestinal wall and regional lymph nodes, and transmural fibrosis. "Although one study involving 1503 individuals failed to confirm the association of gut microbiome composition with ABO or secretor status, the influence of FUT2 genotype on the gut microbiota has been highlighted not only in healthy individuals but also in patients with Crohn's disease." (PMID 28167958, 2017).
dengue (3 papers, 2021 to 2025). "Understanding genetic factors, including the potential association between ABO blood groups and dengue severity, is crucial for identifying individuals at higher risk of developing severe outcomes, such as DHF and DSS." (PMID 39996197, 2025). "The most frequent blood group among dengue infected children in our study was ‘O’ positive in contrast to the most common ABO and Rh blood type (‘B’ positive) noted among healthy donors of the country." (PMID 34715835, 2021).
esophageal squamous cell carcinoma (3 papers, 2014 to 2018). Esophageal squamous cell carcinoma (ESCC) is a type of esophageal carcinoma (EC) that can affect any part of the esophagus, but is usually located in the upper or middle third. "The ABO blood group has been demonstrated to be associated with clinical outcomes of pancreatic cancer, esophageal squamous cell cancer, colon cancer, nasopharyngeal cancer, and breast cancer." (PMID 29109911, 2017). "The current study was undertaken to correlate ABO blood group frequency with squamous cell carcinoma of esophagus in this region to evaluate the utility of ABO blood group as a preclinical marker." (PMID 25054136, 2014).
glaucoma (3 papers, 2009 to 2024). Increased pressure in the eyeball due to obstruction of the outflow of aqueous humor. "In a previous multi-ancestry meta-analysis, the International Glaucoma Genetics Consortium (IGGC) revealed a novel ABO polymorphism (rs8176693) associated with IOP." (PMID 37239387, 2023). "This similarity with the Iranian population has also been observed for the association of the ABO blood groups with different types of glaucoma." (PMID 20029655, 2009). "While FUT2 has been associated with autoimmune diseases such as celiac and Crohn’s, its function in these conditions is linked to the secretion of ABO antigens in gastrointestinal mucosa, and no direct connection to glaucoma has been established." (PMID 38287276, 2024).
graft versus host disease (3 papers, 2020 to 2024). An immune system disorder that occurs after allogeneic hematopoietic stem cell transplant and is a reaction of donor immune cells against host tissues. "Thus, considering allelic ABO sequences, at least 15% of all phenotypically ABO-matched transplant pairs can be expected to have genotype constellations relevant to graft-versus-host disease (GVHD)." (PMID 33329606, 2020). "The current state and future directions for donor selection (sex, age, ABO blood type, and HLA disparity), donor source, the dose of infused CD34+ cells, optimal conditioning, and the concomitant graft-versus-host disease prophylaxis other than PTCY are also extensively discussed." (PMID 38339351, 2024).
hemolysis (3 papers, 2020 to 2026). Disruption of the integrity of the erythrocyte membrane causing release of hemoglobin. "AIHA following AHSCT is distinct from ABO mismatch driven hemolysis, which can arise from either major or minor ABO mismatch between the donor and host." (PMID 32983144, 2020).
hepatitis B (3 papers, 2023 to 2025). "Furthermore, to ensure the safe use of allogeneic PRP, performing ABO and Rh blood typing, along with comprehensive pathogen screening—including HIV, hepatitis B, hepatitis C, and other bloodborne pathogens—is essential." (PMID 39448627, 2024).
hepatocellular carcinoma (3 papers, 2012 to 2024). A malignant tumor that arises from hepatocytes. "However, the role of the ABO blood type in hepatocellular carcinoma (HCC) remains elusive." (PMID 28667286, 2017).
influenza (3 papers, 2012 to 2024). An acute viral infection of the respiratory tract, occurring in isolated cases, in epidemics, or in pandemics; it is caused by serologically different strains of viruses (influenzaviruses) designated A, B, and C, has a 3-day incubation period, and usually lasts for 3 to 10 days. "The 1960’s and 70’s saw a period of interest in the relationship between the ABO blood group and susceptibility to influenza infection." (PMID 22438897, 2012).
liver disease (3 papers, 2012 to 2025). "However, a few previous studies showed relationships between the ABO blood group and liver diseases, including HCC, so the discovery of a relationship between the ABO blood group and HCC is not surprising." (PMID 22235351, 2012).
melanoma (3 papers, 2010 to 2015). A malignant, usually aggressive tumor composed of atypical, neoplastic melanocytes. "To date, ours is the first study to investigate the relationship between ABO blood types and metastasis in patients with cutaneous malignant melanoma, although some studies have been undertaken analysis of such a relationship in tumors." (PMID 24516588, 2014). "Using two large cohorts in the US, we examined ABO blood type and incidence of skin cancer, including melanoma, squamous cell carcinoma (SCC), and basal cell carcinoma (BCC)." (PMID 20694147, 2010). "ABO blood groups have been suggested to contribute to the development of certain tumors; however, the associations between ABO blood groups and the incidence and metastases of cutaneous malignant melanomas have not been fully evaluated in Chinese populations." (PMID 24516588, 2014).
migraine (3 papers, 2021 to 2026). "This study aimed to evaluate the distribution of ABO and Rh blood groups in patients with migraine and to investigate their associations with migraine subtypes, clinical features, and white matter lesions (WMLs)." (PMID 41928142, 2026). "While genetic and vascular mechanisms have been extensively studied, the potential role of the ABO blood group system in migraine susceptibility and clinical characteristics remains unclear." (PMID 41928142, 2026).
ovarian tumor (3 papers, 2021 to 2024). "ABO gene expression was down‐regulated in ovarian tumor tissues compared with adjacent normal tissues (p = 0.013)." (PMID 36415180, 2023). "ABO gene expression was down‐regulated in ovarian tumor tissues compared with paired adjacent normal tissues (p = 0.027)." (PMID 36415180, 2023). "We also identified that ABO gene expression was lower in ovarian tumor tissues than adjacent normal tissues." (PMID 36415180, 2023). "In our study, we found the expression level of NFYB is decreased in ovarian tumor tissues compared with adjacent normal tissues and positive correlation with expression level of ABO gene." (PMID 36415180, 2023). "The expression of A, B histo‐blood group antigens and ABO gene were lower in ovarian tumor tissues than that in their adjacent normal tissues and we also found the possible regulatory factors of ABO gene expression." (PMID 36415180, 2023). "We also found ABO gene expression was down‐regulated in ovarian tumor tissues compared with paired normal tissues of fourteen high‐grade serous ovarian cancer patients, particularly in blood group A patients." (PMID 36415180, 2023). "We compared the target genes identified from normal ovarian cells by the O’Mara group and ovarian tumor cells from our study and found some common targets like ABO at 9q34.2, MYC at 8q24.21, and METTL10 at 10p12.31." (PMID 33815481, 2021). "In addition, we examined the relationship between ABO gene expression and transcription factors/DNA methylation related to ABO gene in ovarian tumor tissues." (PMID 36415180, 2023). "The expression of histo‐blood group antigens and ABO gene expression in ovarian tumor tissues versus adjacent normal tissues were evaluated." (PMID 36415180, 2023).
parasitemia (3 papers, 2011 to 2023). "Possible associations between RhD or ABO blood types and peak parasitemia, the length of hospital stay, and intensive care unit (ICU) admission were evaluated." (PMID 36696414, 2023).
SARS-CoV infection (3 papers, 2020 to 2022). "The ABO blood group polymorphism was seen to be associated in particular with 2002–2003 SARS-CoV infection." (PMID 32946531, 2020). "This locus was located at the ABO blood group, which contributed to the immunopathogenesis of SARS-CoV-infection (The Severe Covid-19 Gwas Group, 2020)." (PMID 36187959, 2022). "In SARS-CoV infection, it has been hypothesized that these antibodies may decrease the rate of infection, and the degree of protection, may be influenced by the ABO antibody titer, secretor status, and incidence of group O in the population." (PMID 38624532, 2020).
sexually transmitted disease (3 papers, 2015 to 2025). A Disease due to or propagated by sexual contact. "We observed that in the first trimester of pregnancy, 45% of the women had access to laboratory tests for ABO/Rh, haemoglobin/haematocrit, and human immunodeficiency virus, in addition to the first urine, blood glucose, and venereal disease research laboratory tests." (PMID 31747914, 2019). "In addition to hemoglobinopathy screening, premarital screening also includes screening for ABO and Rh(D) blood groups, sexually transmitted diseases such as hepatitis B surface antigen, hepatitis C antibody, human immunodeficiency virus antibody, and Trypanosoma pallidum antibody screening." (PMID 40084341, 2025).
skin cancer (3 papers, 2010 to 2024). "However, no prospective cohort study to date has examined the association between ABO blood group and the risk of skin cancer." (PMID 20694147, 2010). "Additional studies are needed to confirm these associations and to define the mechanisms by which ABO blood type or closely linked genetic variants may influence skin cancer risk." (PMID 20694147, 2010).
type 1 diabetes (3 papers, 2019 to 2023). "We further explored a possible link between neonatal jaundice or blood-group incompatibility (Rh and ABO) and risk for type 1 diabetes." (PMID 31041471, 2019). "Interestingly, COVID-19 is also in this community, connected only to Type I Diabetes by the common variant rs657152 in the ABO gene." (PMID 36050444, 2022).
alloimmunization (2 papers, 2023 to 2024). An immune response to foreign (donor) antigens. "In that study, Rh alloimmunization was reported in 16.7% of newborns with HDFN, and the authors estimate HDFN rates due to ABO and Rh alloimmunization of 2.9 and 0.5 per 1000 newborns, respectively." (PMID 39707247, 2024). "Newborns with HDFN with ABO alloimmunization during pregnancy were less likely to receive simple transfusions and exchange transfusions and/or IVIG than those with Rh alloimmunization during pregnancy." (PMID 37229151, 2023).
cystic fibrosis (2 papers, 2013 to 2022). Autosomal recessive disorder caused by pathogenic variants in the CFTR gene (cystic fibrosis transmembrane conductance regulator), which encodes a chloride and bicarbonate channel expressed in epithelial cells, and follow the diagnosis criteria. "The nature of the oligosaccharides present in airways depends not only on ABO, Lewis and secretor genotypes but also on long-term inflammatory diseases such as chronic bronchitis and cystic fibrosis." (PMID 23976992, 2013).
dyslipidaemia (2 papers, 2021 to 2025). "We assessed associations between blood ABO group, smoking and dyslipidaemia in 74,206 women participating in the E3N cohort." (PMID 34290325, 2021). "Thus, the RhD blood group, but not ABO, seems to be associated with dyslipidaemia and may act as a future possible risk marker of cardiovascular disease." (PMID 39844181, 2025).
endometrial carcinoma (2 papers, 2017 to 2025). A malignant tumor arising from the epithelium that lines the cavity of the uterine body. "With regard to gynecologic carcinomas, there is a confined number of studies that explored the relationship between ABO blood group and endometrial carcinoma (EC) in the PubMed-indexed literature." (PMID 29487773, 2017). "While ABO has not been directly linked to endometrial cancer, its differential expression may reflect systemic inflammatory or immune alterations." (PMID 40863222, 2025).
gastric ulcer (2 papers, 2013 to 2021). An ulcerated lesion in the mucosal surface of the stomach. "Therefore, further association analysis is essential to determine the role of ABO variations on gastric ulcer susceptibility." (PMID 23704932, 2013). "Since H. pylori infection and non-steroidal anti-inflammatory drugs induce gastroduodenal mucosal injury which would cause duodenal and gastric ulcer, we examined the role of variants in the PSCA and ABO genes on gastric ulcer risk among Japanese population." (PMID 23704932, 2013).
gastrointestinal infections (2 papers, 2020 to 2025). "The risk allele was associated with reduced ABO expression, providing, for the first time, genetic evidence to support previous studies linking the O blood group to gastrointestinal infections." (PMID 32152699, 2020). "We identified a genome-wide significant locus associated with susceptibility to gastrointestinal infections (OR = 1.13; 95% CI: 1.08–1.18, P = 2.9 × 10–8), where the top SNP was an eQTL for the ABO gene." (PMID 32152699, 2020). "We have also estimated the contribution of common SNPs to susceptibility to gastrointestinal infections and identified a genome-wide significant association; one allele, independently associated with lower expression levels of ABO, increased the risk of having gastrointestinal infections." (PMID 32152699, 2020). "Thus, our results are in line with the suggestion that blood type O, or lower expression of the ABO gene and potentially of antigens A or B, in this case, may be associated with gastrointestinal infections." (PMID 32152699, 2020).
laryngeal carcinoma (2 papers, 2016 to 2017). Carcinoma that arises from the laryngeal epithelium. "Our study showed, by both univariate and multivariate analyses, that the ABO blood group was an independent prognostic factor for patients with laryngeal cancer." (PMID 27733208, 2016). "Several previous studies, which, taken together, included a relatively small number of patients, examined the relationship between the ABO blood group and the incidence of laryngeal cancer." (PMID 27733208, 2016). "The purpose of this study was to elucidate the association between the ABO blood group and the clinicopathologic characteristics of patients with laryngeal cancer and determine whether a specific ABO blood group is an independent predictor of prognosis." (PMID 27733208, 2016).
lung carcinoma (2 papers, 2015 to 2022). "The ABO blood group distribution of each lung cancer type group was compared with that of the control group." (PMID 36464709, 2022). "The results showed that there were significant differences in ABO blood group composition between lung cancer group and control group (P < 0.01)." (PMID 36464709, 2022).
mental disorder (2 papers, 2020 to 2025). A disease that has its basis in the disruption of mental process. "Accordingly, familial aggregation of neurodevelopmental and mental disorders expectably shows partly redundant associations with ABO blood groups." (PMID 39781374, 2025). "We emphasize that, as we employed a covariate for psychiatric diagnosis in our GWAS, it does not seem to be the case that the link with the ABO gene discovered in this study reflects a direct, causal link between blood groups and psychiatric disorders through association with this SNP." (PMID 32152699, 2020).
osteoporosis (2 papers, 2020 to 2025). A condition of reduced bone mass, with decreased cortical thickness and a decrease in the number and size of the trabeculae of cancellous bone (but normal chemical composition), resulting in increased fracture incidence. "This was also an intriguing finding given that ABO blood groups have been known to associate with osteoporosis and osteoporosis severity." (PMID 32198180, 2020). "ABO antigens are glycoproteins present in the body and possibly even in bone tissue, suggesting a biological link between ABO blood groups and osteoporosis." (PMID 40598733, 2025).
periodontal disease (2 papers, 2021 to 2024). "This study investigates the relationship between erythrocyte sedimentation rate (ESR) and ABO blood grouping in the context of periodontal disorders." (PMID 39219881, 2024). "Nevertheless, long-term follow-up studies with varying geographic distribution and inclusion of periodontally healthy individuals are required to make a detailed assessment of the influence of ABO blood groups on periodontal diseases." (PMID 34057339, 2021).
pneumonia (2 papers, 2022 to 2023). An acute, acute and chronic, or chronic inflammation focally or diffusely affecting the lung parenchyma, caused by an infection in one or both of the lungs (by bacteria, viruses, fungi, or mycoplasma.). "Specifically, through a univariate regression analysis, we evaluated the association between risk allele carrier status for each genetic variant (OAS1/2/3, DPP9, IFNAR2, LZTFL1, ABO, and FUT2) and the development of clinical complications and of pneumonia." (PMID 36873632, 2023).
preeclampsia (2 papers, 2011 to 2014). Preeclampsia is a hypertensive disorder of pregnancy that is characterized by new-onset hypertension with proteinuria presenting after 20 weeks of gestation, and depending on mild or severe forms may initially present with severe headache, visual disturbances, and hyperreflexia. "Adjustment of PP13 MoMs to maternal ABO blood group improved the prediction accuracy of first trimester maternal serum PP13 MoMs for preeclampsia and IUGR." (PMID 21799738, 2011).
Rotavirus infection (2 papers, 2019 to 2022). Infection with any of the rotaviruses. "Pearson’s chi-squared test and Fisher’s exact tests revealed there is an association between rotavirus infection and the ABO groups, Lewis antigens, secretor status, and combined secretor and Lewis categories (all had p values less than 0.05)." (PMID 36560739, 2022). "In order to evaluate the role of HBGAs in rotavirus infections in our population, secretor status (FUT2+), ABO blood group, and Lewis antigens were determined in children attended for rotavirus gastroenteritis in Valencia, Spain." (PMID 30974776, 2019).
sickle cell disease (2 papers, 2023 to 2025). Sickle cell anemias are chronic hemolytic diseases that may induce three types of acute accidents: severe anemia, severe bacterial infections, and ischemic vasoocclusive accidents (VOA) caused by sickle-shaped red blood cells obstructing small blood vessels and capillaries. "This case demonstrates the complex interplay of alloimmunization, weak ABO subtypes, and transfusion complications in a high-risk patient with sickle cell disease." (PMID 41244812, 2025).